KDM7A (lysine demethylase 7A)
Description:
Histone demethylase required for brain development. Specifically demethylates dimethylated 'Lys-9', 'Lys-27' and 'Lys-36' (H3K9me2, H3K27me2, H3K36me2, respectively) of histone H3 and monomethylated histone H4 'Lys-20' residue (H4K20Me1), thereby playing a central role in histone code. Specifically binds trimethylated 'Lys-4' of histone H3 (H3K4me3), affecting histone demethylase specificity: in presence of H3K4me3, it has no demethylase activity toward H3K9me2, while it has high activity toward H3K27me2. Demethylates H3K9me2 in absence of H3K4me3. Has activity toward H4K20Me1 only when nucleosome is used as a substrate and when not histone octamer is used as substrate.
Synonyms: JHDM1D; KIAA1718
Tractability: Small molecule: a structure with a bound ligand is known; a high-quality ligand is known. PROTAC: ubiquitination databases record sites on it; a small molecule that binds it is known.
Target class: Epigenetic regulator; Jumonji domain-containing; Eraser; Lysine demethylase
Gene: Protein-coding gene on chromosome 7 (140,084,746 to 140,177,055, reverse strand). Ensembl gene ENSG00000006459.
Subcellular location: Nucleus
Subcellular location (Human Protein Atlas): Nucleoplasm; Nucleoli
Pathways (Reactome):
Chromatin organization: HDMs demethylate histones
Disease: Signaling by BRAF and RAF1 fusions
Gene Ontology:
Molecular function: 2-oxoglutarate-dependent dioxygenase activity; histone H3K27me2/H3K27me3 demethylase activity; histone H3K36 demethylase activity; histone H3K9 demethylase activity; histone H3K9me/H3K9me2 demethylase activity; histone H4K20 demethylase activity; iron ion binding; zinc ion binding; histone demethylase activity; transcription coregulator activity
Biological process: chromatin remodeling; midbrain development; regulation of transcription by RNA polymerase II; positive regulation of DNA-templated transcription
Cellular component: nucleoplasm; nucleus
Genetic constraint (gnomAD): Loss-of-function variants: 14 observed, 54.05 expected, observed/expected ratio (o/e) 0.26, 90% interval 0.17 to 0.41. The upper end of that interval is the gene's LOEUF score, 0.41, which puts it in group 1 of 6, group 1 being the genes least tolerant of losing a copy. Missense variants: 616 observed, 696.4 expected, observed/expected ratio (o/e) 0.88, 90% interval 0.83 to 0.94. Synonymous variants: 284 observed, 254.77 expected, observed/expected ratio (o/e) 1.11, 90% interval 1.01 to 1.23.
Homologues: Orthologues: chimpanzee KDM7A (99% identical), macaque KDM7A (98% identical), dog KDM7A (95% identical), pig KDM7A (93% identical), rat Kdm7a (91% identical), mouse Kdm7a (90% identical), rabbit KDM7A (87% identical), guinea pig KDM7A (85% identical), tropical clawed frog kdm7a (67% identical), zebrafish kdm7ab (56% identical), Caenorhabditis elegans jmjd-1.2 (18% identical), Caenorhabditis elegans jmjd-1.1 (16% identical), and 1 more. Paralogues in human: PHF8 (41% identical), PHF2 (40% identical), KDM2B (25% identical), KDM2A (21% identical).
Diseases named in the same sentence as KDM7A in open-access papers:
KDM7A is named in the same sentence as 31 diseases in open-access papers, as found by Europe PMC text mining. Sharing a sentence is not in itself a finding about the gene and the disease. The quoted sentences say what the papers report.
breast carcinoma (8 papers, 2021 to 2024). "The expression of circ_002178 was positively associated with the presence of KDM7A in breast cancer patient tumor tissues, however, miR-1258 was oppositely associated." (PMID 39170516, 2024). "KDM7A encodes a dual histone demethylase capable of promoting Bcl-2 upregulation and thereby suppressing apoptotic cell death in breast cancer." (PMID 34661511, 2021). "Similarly, KDM7A was shown to be associated with stem cell maintenance in breast cancer and a reduction in apoptosis." (PMID 38943031, 2024). "Circ_002178 was shown to downregulate miR-1258 levels and decrease miR-1258's suppressive effect on KDM7A, so promotes the stem-like properties of breast cancer cells." (PMID 39170516, 2024). "KDM7A was identified as a tumor promoter in breast cancer, and its low expression inhibited tumor growth." (PMID 39170516, 2024). "Further analysis confirmed that the H3K9/H3K27 dual demethylase JHDM1D/KDM7A was essential for TGF-β-induced RHOJ transcription in breast cancer cells." (PMID 34249916, 2021). "Small-molecule inhibitors of KDM7A have been discovered although their therapeutic potentials in breast cancer have yet to be explored." (PMID 34249916, 2021). "In the present study, we delineate a novel pathway wherein MKL1 recruits the histone H3K9/H3K27 demethylase JHDM1D/KDM7A to regulate breast cancer metastasis through epigenetically activating RHOJ transcription." (PMID 34249916, 2021). "Next, two different animal models were exploited to evaluate the effect of KDM7A knockdown on breast cancer cell migration/invasion in vivo." (PMID 34249916, 2021). "Exposure of breast cancer cells to TGF-β led to an upregulation of KDM7A expression at both mRNA and protein levels." (PMID 34249916, 2021). "Wound healing assay and transwell assay demonstrated that KDM7A knockdown blockaded TGF-β-induced breast cancer cell migration and invasion." (PMID 34249916, 2021). "We next evaluated the functional relevance of KDM7A in the migration/invasion of breast cancer cells in vitro and in vivo." (PMID 34249916, 2021). "KDM7A knockdown attenuated migration and invasion of breast cancer cells in vitro and mitigated the growth and metastasis of breast cancer cells in nude mice." (PMID 34249916, 2021). "Finally, by comparing the expression patterns of components of the TGF signaling pathway and KDM7A in human breast cancer specimens, we discovered that there was statistically significant correlation between KDM7A and TGFB2/SMAD2/SMAD3/SMAD4." (PMID 34249916, 2021). "KDM7A silencing significantly suppressed the metastatic abilities of breast cancer cells." (PMID 34249916, 2021). "Additionally, miR-1258 could constrain cell proliferation, migration, and invasion, and regulate stem-like cell properties in breast cancer via regulating lysine demethylases 7A (KDM7A)." (PMID 35582196, 2022). "We proposed that JHDM1D/KDM7A could participate in RHOJ induction by TGF-β in breast cancer cells." (PMID 34249916, 2021). "We also found that the expression of KDM7A was upregulated in chemoresistant cells (MCF-7/Adr and MCF-7/Tax), while MAPT and PP14571 were downregulated compared with the chemosensitive breast cancer control cell group (MCF-7/Con)." (PMID 34661511, 2021). "KDM7A expression level, either singularly or in combination with that of RHOJ, could be used to predict prognosis in breast cancer patients." (PMID 34249916, 2021). "In addition, expression data extracted from the public cancer database (TCGA) showed a highly correlative relationship between KDM7A expression and RHOJ expression in human breast cancer tissues." (PMID 34249916, 2021). "Both MKL1 and KDM7A seemed to be essential for RHOJ trans-activation in breast cancer cells raising the possibility that MKL1 might interact with and recruit KDM7A to the RHOJ promoter." (PMID 34249916, 2021).
breast carcinoma (continued). "Although we show here that KDM7A is potentially important for the malignant spread of breast cancer cells, this observation is unlikely to be easily explained by its activation of RHOJ transcription." (PMID 34249916, 2021).
prostate carcinoma (6 papers, 2020 to 2026). A carcinoma that arises from epithelial cells of the prostate gland. "More importantly, the effect of the KDM7A inhibitor TC-E 5002 on prostate cancer cell proliferation was analyzed, and we observed that prostate cancer cell growth was reduced on treatment with TC-E 5002 treatment." (PMID 32781788, 2020). "A recently published paper from our research group described the H3K27 demethylase activity of KDM7A on the response elements of AR target genes in prostate cancer." (PMID 32781788, 2020). "Another study showed that KDM7A is related to enzalutamide resistance in prostate cancer, suggesting that KDM7A may be a prevalent marker for tumour drug resistance." (PMID 38943031, 2024). "Additionally, KDM7A also was significantly up-regulated in prostate cancer tissue, and the silencing of KDM7A significantly inhibited breast tumor growth in vivo." (PMID 32914833, 2020). "Since KDM7A is known to regulate AR activity in prostate cancer cells, we speculated that it may control AR activity as an epigenetic regulator in bladder cancer cells." (PMID 32781788, 2020). "In our analysis, twelve histone demethylases showed gene upregulation in prostate cancers, of which six (KDM1A, KDM4B, KDM5B, KDM5C, KDM7A, and PHF8) were in line with previous reports." (PMID 36776320, 2023).
bladder cancer (3 papers, 2020 to 2024). "High KDM7A mRNA expression was associated with significantly worse overall survival (OS) in men with stage 2 bladder cancer." (PMID 32781788, 2020). "Further experiments showed that inhibiting KDM7A reduced the cisplatin resistance of bladder cancer cells." (PMID 38943031, 2024). "To verify the effect of KDM7A in bladder cancer cell migration and metastasis, we measured migration and invasion in KDM7A knock-down T24 and J82 bladder cancer cells." (PMID 32781788, 2020). "Biochemical studies revealed that KDM7A knockdown in the bladder cancer cells repressed the activity of androgen receptor (AR) through epigenetic regulation." (PMID 32781788, 2020). "Here, we have focused on the role of KDM7A in bladder cancer cells, especially under drug-resistant conditions." (PMID 32781788, 2020). "When the KDM7A gene was knocked down, bladder cancer cell lines showed impaired cell growth, increased cell death, and reduced rates of cell migration." (PMID 32781788, 2020). "In the present study, we found that the bladder cancer cells expressing KDM7A shRNA also showed decreased cell proliferation." (PMID 32781788, 2020). "On the other hand, when we used TC-E 5002, a chemical inhibitor of KDM7A, we detected a relatively small effect on T24 bladder cancer cell growth compared to the inhibition effect of KDM7A knock-down." (PMID 32781788, 2020). "The T24 bladder cancer cells expressing control or KDM7A shRNA were treated with DHT, sonicated, and the chromatin was precipitated with AR antibody." (PMID 32781788, 2020). "To investigate the role of KDM7A in bladder tumor growth in vivo, we stably incorporated a luciferase-expressing vector into KDM7A shRNA-expressing bladder cancer cell lines and control cell line." (PMID 32781788, 2020). "In order to analyze KDM7A expression in bladder cancer patients, we performed immunohistochemistry (IHC) of KDM7A using tissue microarray." (PMID 32781788, 2020). "To analyze the function of KDM7A histone demethylase in bladder cancer cells, we produced KDM7A knock-down bladder cell lines (T24 and J82), using a lenti-viral shRNA expression system." (PMID 32781788, 2020). "After confirming an increase in AR activity in CR-T24 cells, we utilized the KDM7A inhibitor TC-E 5002, in conjunction with AR antagonist enzalutamide, to evaluate the role of KDM7A on bladder cancer growth and drug resistance in terms of the AR pathway." (PMID 32781788, 2020). "We examined the prognostic value of KDM7A expression at each tumor stage, and in both men and women, in the bladder cancer database using KDM7A as the ‘key gene’ for data mining." (PMID 32781788, 2020). "Our data confirmed the molecular function of KDM7A on AR transcription factor activity in bladder cancer cells." (PMID 32781788, 2020). "Although the morphology of KDM7A knock-down cells was not different from control cells, the rate of cell proliferation in KDM7A knock-down bladder cancer cells was reduced compared to that of control shRNA-expressing cells." (PMID 32781788, 2020). "In the present study, we have further investigated the role of KDM7A in the epigenetic regulation of AR in BCa, with a focus on the regulation of AR activity in the cisplatin-resistant bladder cancer cells." (PMID 32781788, 2020). "Upon treatment with TC-E 5002, a chemical inhibitor of KDM7A, the cisplatin-resistant bladder cancer cells, showed decreased cell proliferation." (PMID 32781788, 2020). "KDM7A stimulates cell growth and migration and impairs cell death in bladder cancer." (PMID 38943031, 2024). "Although further in-depth research is needed to validate the results of our study, our findings suggest that KDM7A could be a new target for treating bladder cancer and overcoming drug resistance, in conjunction with an AR inhibitor." (PMID 32781788, 2020). "The findings suggest that histone demethylase KDM7A mediates the growth of bladder cancer." (PMID 32781788, 2020).
bladder cancer (continued). "We also observed the upregulation of KDM7A expression in patients with bladder cancer." (PMID 32781788, 2020). "Our finding that the protein and mRNA levels of KDM7A are increased in bladder cancer tissues may point to elevated AR activity in the cancer." (PMID 32781788, 2020). "The findings suggest that KDM7A is required for cell migration and EMT transition in bladder cancer cells." (PMID 32781788, 2020).
Hepatic steatosis (3 papers, 2021 to 2024). Steatosis is a term used to denote lipid accumulation within hepatocytes. "Based on these findings, we propose an epigenetic model of KDM7A associated with the development of hepatic steatosis." (PMID 34681759, 2021). "Taken together, these results indicate that KDM7A overexpression induces hepatic steatosis through upregulation of DGAT2 by erasing H3K9me2 and H3K27me2 on the promoter." (PMID 34681759, 2021). "Here, we studied the functional role of the histone demethylase KDM7A in the development of hepatic steatosis." (PMID 34681759, 2021). "Taken together, our results indicate that KDM7A overexpression in the liver induces hepatic steatosis in mice." (PMID 34681759, 2021). "To understand the functional role of KDM7A in hepatic steatosis in vivo, we injected recombinant Ad-KDM7A through the tail vein of C57BL/6J mice to overexpress hepatic KDM7A." (PMID 34681759, 2021). "In conclusion, KDM7A plays a pivotal role in the development of hepatic steatosis by upregulating DGAT2 expression." (PMID 34681759, 2021). "Therefore, the in vivo data show that KDM7A is an epigenetic regulator involved in the development of hepatic steatosis through the upregulation of DGAT2 expression." (PMID 34681759, 2021). "It is uncertain whether the KDM7A-induced hepatic steatosis shown in the present study favors the development of NASH and liver injuries." (PMID 34681759, 2021). "We ascertained the functional role of KDM7A in the pathogenesis of hepatic steatosis in vivo." (PMID 34681759, 2021). "Additionally, adenovirus-mediated overexpression of KDM7A in mice resulted in hepatic steatosis, which was accompanied by increased expression of hepatic DGAT2." (PMID 34681759, 2021). "We used gain-of-function and loss-of-function studies in AML12 cells to determine whether KDM7A induces hepatic steatosis." (PMID 34681759, 2021). "To determine whether the expression of KDM7A and DGAT2 correlates with hepatic steatosis pathogenesis, we examined the expression of KDM7A and DGAT2 in hepatic steosis-induced cell and animal models." (PMID 34681759, 2021). "In the present study, we investigated whether KDM7A plays a role in the development of hepatic steatosis through the upregulation of DGAT2 in vitro and in vivo." (PMID 34681759, 2021). "In addition, we examined the enrichment of repressive histone marks H3K9me2 and H3K27me2 on the promoter of DGAT2 in KDM7A-overexpressing AML12 cells and assessed the development of hepatic steatosis in vivo in KDM7A-overexpressing mice." (PMID 34681759, 2021). "Therefore, we believe that DGAT2 may be a potential downstream target gene of KDM7A necessary for the development of hepatic steatosis." (PMID 34681759, 2021). "Thus, KDM7A contributes to the development of hepatic steatosis." (PMID 34681759, 2021). "Taken together, these results indicate that KDM7A upregulates the expression of DGAT2, thereby possibly playing a key role in the development of hepatic steatosis." (PMID 34681759, 2021). "Together, these results indicate that KDM7A promotes DGAT2 expression, leading to increased intracellular TG accumulation, and consequently results in the development of hepatic steatosis." (PMID 34681759, 2021). "However, under hepatic steatosis states such as obesity, KDM7A is overexpressed and erases repressive H3K9me2 and H3K27me2 on the promoter of DGAT2, which leads to increased TG accumulation and results in hepatic steatosis." (PMID 34681759, 2021). "However, the role of KDM7A in the development of hepatic steatosis has not been elucidated." (PMID 34681759, 2021). "Accordingly, we hypothesized that KDM7A epigenetically upregulates DGAT2 expression by erasing the transcriptionally repressive histone marks H3K9me2 and H3K27me2 on the promoter of DGAT2, eventually leading to hepatic steatosis through increasing TG synthesis." (PMID 34681759, 2021).
osteoporosis (3 papers, 2019 to 2024). A condition of reduced bone mass, with decreased cortical thickness and a decrease in the number and size of the trabeculae of cancellous bone (but normal chemical composition), resulting in increased fracture incidence. "Further research needs to be conducted to more conclusively determine the relevance of KDM7A to human bone disorders such as osteoporosis." (PMID 38346941, 2024). "In conclusion, these results show that Liuwei Dihuang pill is beneficial to diabetic nephropathy-related osteoporosis by suppressing inflammation, in part, through down-regulation of KDM7A and Wnt/β-catenin signaling pathway." (PMID 32914833, 2020). "Our study suggests that KDM7A balances adipogenic and osteogenic differentiation from progenitor cells through epigenetic control of C/EBPα and canonical Wnt signalling and implicates that control of KDM7A action has an epigenetic perspective of curtailing metabolic disorders like osteoporosis." (PMID 30614617, 2019). "Consequently, inhibiting KDM7A may prove beneficial in ameliorating osteoporosis." (PMID 38346941, 2024). "In the present study, we found that LWDH could attenuate DN-induced osteoporosis by inhibiting inflammation and EMT, which was significantly dependent on the blockage of KDM7A and Wnt/β-catenin signaling pathway." (PMID 32914833, 2020).
pancreatic cancer (2 papers, 2015 to 2019). "Taken together, these data supported the results of our cell-based study and suggested that G9a may orchestrate PCL3 and KDM7A to inhibit E-cadherin in pancreatic cancer." (PMID 26688070, 2015).
atherosclerosis (1 paper, 2024). A disease characterized by the build-up of fatty material and calcium deposition in the arterial wall resulting in partial or complete occlusion of the arterial lumen. "As KDM7A responds to d‐flow and is involved in inflammation, it is worth examining whether it participates in the development of atherosclerosis." (PMID 39643939, 2024).
bladder tumor (1 paper, 2020). "In the mouse xenograft model, KDM7A knockdown or treatment with its inhibitor reduced the growth of the bladder tumor." (PMID 32781788, 2020).
lymph node metastasis (1 paper, 2024). "In addition to high miR-451a and KDM7A expression, lymph node metastasis and tumour size are also risk factors for cetuximab resistance." (PMID 38943031, 2024). "The results showed that among all variables, tumour size, lymph node metastasis, TNM stages III and IV, high miR-451a expression and high KDM7A expression had significant impacts on cetuximab resistance." (PMID 38943031, 2024).
mental retardation (1 paper, 2023). "Among the KDM7 demethylases, PHF8 has been involved in the regulation of X-linked mental retardation genes including KDM5C, and KDM7A has significant roles in the neuronal differentiation of mouse embryonic stem cells." (PMID 36975603, 2023).
steatosis (1 paper, 2021). Increased lipid within the cytoplasm of cells. "The appearance of the liver revealed that Ad-KDM7A-injected mice increased steatosis." (PMID 34681759, 2021).